UBL3 (ubiquitin like 3)
Synonyms: PNSC1; HCG-1; DKFZP434K151; FLJ32018
Tractability: Antibody: UniProt places it where antibodies can reach, with medium confidence; its Gene Ontology location is reachable by antibodies, with medium confidence. PROTAC: its protein half-life has been measured.
Gene: Protein-coding gene on chromosome 13 (29,764,371 to 29,850,617, reverse strand). Ensembl gene ENSG00000122042.
Subcellular location: Cell membrane
Subcellular location (Human Protein Atlas): Centrosome
Gene Ontology:
Molecular function: protein binding
Cellular component: extracellular exosome; plasma membrane
Genetic constraint (gnomAD): Loss-of-function variants: 6 observed, 17.11 expected, observed/expected ratio (o/e) 0.35, 90% interval 0.19 to 0.69. The upper end of that interval is the gene's LOEUF score, 0.69, which puts it in group 2 of 6, group 1 being the genes least tolerant of losing a copy. Missense variants: 108 observed, 144.38 expected, observed/expected ratio (o/e) 0.75, 90% interval 0.64 to 0.88. Synonymous variants: 49 observed, 49.58 expected, observed/expected ratio (o/e) 0.99, 90% interval 0.79 to 1.25.
Homologues: Orthologues: chimpanzee UBL3 (100% identical), macaque UBL3 (100% identical), guinea pig UBL3 (99% identical), mouse Ubl3 (99% identical), rat Ubl3 (93% identical), zebrafish ubl3a (93% identical), dog UBL3 (83% identical), tropical clawed frog ubl3 (69% identical), Caenorhabditis elegans C46F11.6 (56% identical).
Diseases named in the same sentence as UBL3 in open-access papers:
UBL3 is named in the same sentence as 25 diseases in open-access papers, as found by Europe PMC text mining. Sharing a sentence is not in itself a finding about the gene and the disease. The quoted sentences say what the papers report.
breast carcinoma (8 papers, 2018 to 2025). "Furthermore, we comprehensively identified UBL3-associated molecules in MDA-MB-231 human breast cancer cells." (PMID 39148092, 2024). "MDA-MB-231 cells, a human breast cancer line, has been used to elucidate UBL3 as a post-translational modification factor, were treated with doxycycline (DOX) for 1.5 h." (PMID 39498724, 2024). "In summary, UBL3 may play an important function in the process of invasion and metastasis of breast cancer, but further studies are needed to verify this." (PMID 36674743, 2023). "In the MDA-MB-231 human breast cancer cell line, PTM of substrate proteins by UBL3 was shown to depend on cysteine residues in the C-CAAX sequence (C113/C114) of UBL3." (PMID 35197392, 2022). "To clarify the role of UBL3 as a PTM factor, we expressed Flag-UBL3 in MDA-MB-231 breast cancer cells and purified UBL3 proteins by immunoprecipitation, followed by western blotting with UBL3 antiserum." (PMID 30258067, 2018).
lung carcinoma (5 papers, 2020 to 2025). "Consistently, bioinformatic analysis revealed that UBL3 and PD-L1 expression levels affect lung cancer survival." (PMID 41398009, 2025). "This seems to explain the downregulation of UBL3 and the correlation between UBL3 expression and survival in lung cancer." (PMID 36674743, 2023). "Recent work further characterized ATMIN and UBL3 as two potential tumor suppressors in lung cancers." (PMID 38188687, 2023). "We verified the effects of siRNA against UBL3 (siUBL3) on lung cancer cells, and found that siUBL3 treatment resulted in a reduction of UBL3 protein expression and increased viability of A549 and H1975 cells." (PMID 32296577, 2020). "These possibilities and whether UBL3 could be a therapeutic target for lung cancer warrant further investigation." (PMID 32296577, 2020). "However, the role of UBL3 in lung cancer remains poorly understood." (PMID 32296577, 2020).
cervical carcinoma (2 papers, 2015 to 2025). A carcinoma arising from either the exocervical squamous epithelium or the endocervical glandular epithelium. "Recently, UBL3 was reported to be upregulated in human prostate cancer cells and act as a predictor for relapse and survival in patients with cervical carcinoma or esophageal cancer." (PMID 40548297, 2025). "PDCD6 gene expression was higher in cells sensitive to L-OHP, whileexpression of PDS5B, UBL3, MTIF3,XPO4, CASC8, and GTF3A was lower.UBL3 was identified as one of seven genes that predict relapse andsurvival in early-stage cervical carcinoma patients." (PMID 26678268, 2015).
esophageal cancer (2 papers, 2023 to 2025). A primary or metastatic malignant neoplasm involving the esophagus. "Promoter methylation and downregulation of the UBL3 gene were found in patients with esophageal cancer in northeast India." (PMID 36674743, 2023).
Huntington disease (2 papers, 2024). Huntington disease (HD) is a rare neurodegenerative disorder of the central nervous system characterized by unwanted choreatic movements, behavioral and psychiatric disturbances and dementia. "Therefore, we hypothesized that UBL3 may be involved in the pathological processes associated with the delivery and accumulation of mHTT in the neurons of Huntington’s disease (HD) patients." (PMID 39449505, 2024). "We visualized the distribution of UBL3 in postmortem brain tissue, specifically within the neurons of the striatum in Huntington’s disease (HD) patients, and identified its interaction with polyQ-expanded huntingtin fragments." (PMID 39449505, 2024). "While previous research has predominantly focused on its interactions with α-synuclein, this study investigates UBL3’s role in Huntington’s disease (HD)." (PMID 39449505, 2024). "Overall, our findings provide new insights into the pathology of Huntington’s disease and suggest that modulation of the UBL3 pathway may serve as a potential therapeutic target in the near future." (PMID 39449505, 2024). "We confirmed the association of endogenous UBL3 with the RNA-binding proteins FUS and HPRT1—both listed in the Neurodegenerative Diseases Variation Database (NDDVD)—and with LYPLA1, which is involved in Huntington’s disease, using immunoprecipitation (IP)-western blotting analysis." (PMID 39148092, 2024).
lung squamous cell carcinoma (2 papers, 2020 to 2025). "To evaluate the prognostic significance of UBL3 and PD-L1 expression levels, we analyzed the survival among lung squamous cell carcinoma patients in a public database." (PMID 41398009, 2025). "In both lung adenocarcinoma (LUAD, n = 517) and lung squamous cell carcinoma (LUSC, n = 501), the expression of UBL3 was significantly higher in normal tissues than in tumor lung samples (P < 0.0001)." (PMID 32296577, 2020).
synucleinopathies (2 papers, 2023 to 2024). "Overall, our findings provide new insights and ideas for promoting the modulation of UBL3 as a therapeutic agent for the treatment of synucleinopathy-associated neurodegenerative diseases." (PMID 39000460, 2024). "We hypothesize that MGST3 acts as a modulator to regulate the interaction of α-syn with UBL3 and mediates the sorting of α-syn into small extracellular vesicles, which would provide a new idea to remove the intracellular α-syn accumulation and thus provide a treatment for synucleinopathies." (PMID 39000460, 2024). "Therefore, the UBL3 pathway may be a new therapeutic target for α-synucleinopathies in the future." (PMID 37371780, 2023).
bladder cancer (1 paper, 2023). "Considering the UBL3-interacting proteins, bladder cancer, and liver fibrosis, the latter of which is a major risk factor for hepatocellular carcinoma, may also be related to UBL3." (PMID 36674743, 2023).
gastric cancer (1 paper, 2023). A primary or metastatic malignant neoplasm involving the stomach. "One article reported that UBL3 was significantly downregulated in gastric cancer by RNA-seq measuring 24 pairs of cancerous tissues versus normal gastric tissues." (PMID 36674743, 2023).
Hypercholesterolemia (1 paper, 2025). An increased concentration of cholesterol in the blood. "Furthermore, we found that statins, commonly prescribed for hypercholesterolemia, inhibit UBL3 modification, thereby reducing PD-L1 sorting to sEVs." (PMID 41398009, 2025).
hyperlipidemia (1 paper, 2025). "Therefore, we investigated the effects of statins, which inhibit prenylation and are widely used as therapeutic agents for hyperlipidemia, on UBL3 modification." (PMID 41398009, 2025).
Immunodeficiency (1 paper, 2023). Failure of the immune system to protect the body adequately from infection, due to the absence or insufficiency of some component process or substance. "Further studies are needed to determine whether tumorigenesis mediated by immunodeficiency is related to UBL3 and whether UBL3 overexpression can improve the body’s immune response to tumors." (PMID 36674743, 2023).
melanoma (1 paper, 2021). A malignant, usually aggressive tumor composed of atypical, neoplastic melanocytes. "These genes along with their activation values Eq for melanoma (MEL) are, GPNMB (MEL activation = 18.59), UBL3 (MEL activation = 1.39), AP1S2 (MEL activation = 1.28), RAB38 (MEL activation = 0.91), EDNRB (MEL activation = 0.55), JUN (MEL activation = 0.34), and C1orf21 (MEL activation = -0.13)." (PMID 34570764, 2021).
retinal degeneration (1 paper, 2023). Degeneration of the retina. "Therefore, we propose that UBL3 may play a role in the sorting of proteins towards the photoreceptor outer segment, further explaining the development of PDE6D-associated retinal degeneration." (PMID 36672247, 2023).
tumor (7 papers, 2020 to 2025). "If UBL3 can cause infiltration of DCs CD4+ and CD8+ in tumors, which, in turn, enhances the body’s immune response to tumor cells, this would address the problem of tumor immunosuppression from another perspective." (PMID 36674743, 2023). "In paired tumor adjacent samples from TCGA datasets, UBL3 expression in tumor tissues was lower than that in the adjacent lung samples (P < 0.0001)." (PMID 32296577, 2020). "Here, we found that UBL3 expression was reduced in tumor samples from both TCGA and Oncomine datasets and in 86 NSCLC samples from our laboratory." (PMID 32296577, 2020). "UBL3 expression was decreased in tumor samples compared to that in paired normal lung tissues in 59/86 (68.6%) NSCLCs, was correlated with TNM stage and sex of NSCLC patients, and was significantly higher in non-smoking patients than in smoking patients." (PMID 32296577, 2020). "Hematoxylin-eosin (HE) and Ki67 staining of lung sections confirmed the tumor-inhibitory effect of UBL3." (PMID 32296577, 2020). "Notably, UBL3 was associated with Activated CD8 T cells and pro-inflammatory pathways, highlighting its contradictory involvement in immune activation and tumour growth." (PMID 40475773, 2025). "For the alternative hypothesis, UBL3 is involved in the dissemination of tumor factors mediated through sEVs, promoting tumor metastasis, invasion, and drug resistance." (PMID 36674743, 2023). "In summary, UBL3 may act as a promoter of tumor invasion and metastasis in GC, while there is inconsistency about the apparent downregulation of UBL3 in GC." (PMID 36674743, 2023). "However, why UBL3 was suppressed in tumor samples and how it suppressed cell proliferation, warrant further investigation." (PMID 32296577, 2020). "Western blot assays of tumor lysates indicated overexpression of UBL3 in vivo." (PMID 32296577, 2020). "We found that UBL3 significantly decreased the tumor burden and extended the life span of the mice." (PMID 32296577, 2020). "Although the current results clearly demonstrate that UBL3 modification regulates PD-L1 sorting to sEVs and that this process can be inhibited by statins in vitro, it remains to be determined whether these effects translate into enhanced anti-tumor immune responses in vivo." (PMID 41398009, 2025). "In TCGA database, the expressions of four potential tumor suppressor genes (UBL3, TRIM22, UBE2G2, and MARCH1) were significantly downregulated in tumor samples compared to that in normal lung tissues." (PMID 32296577, 2020). "There is also potential for UBL3 function in cancers that tumor tissues lead to defective MHC II ubiquitination through downregulation of UBL3, thus, affecting DC cell function as one approach for tumor cell immune escape." (PMID 36674743, 2023). "This gives rise to the speculation that UBL3 may maintain dendritic cell function and immunity by mediating MARCH ubiquitination of MHC II and stimulating the body’s immune response to tumor cells." (PMID 36674743, 2023). "We investigated UBL3 RNA levels in TCGA dataset containing 1, 018 NSCLC tumor samples and 110 normal lung specimens and found significantly reduced expression of UBL3 in NSCLC tumor samples compared to that in normal lung tissue samples." (PMID 32296577, 2020).
cancer (5 papers, 2020 to 2025). A tumor composed of atypical neoplastic, often pleomorphic cells that invade other tissues. "The association of UBL3 with several other cancers has also been provided." (PMID 36674743, 2023). "We mainly introduce UBL3 and its functions and summarize the current findings of UBL3 and examine its potential as a therapeutic target in cancers." (PMID 36674743, 2023). "Particularly, we highlight UBL3’s function, its relationship with various cancers, and the potential in cancer therapy." (PMID 36674743, 2023). "Overall, there is a relationship between UBL3 and the development, metastasis, and prognosis of some cancers, but more in-depth studies are still needed." (PMID 36674743, 2023). "Using UBL3, an emerging Ubl, as a targeting site to regulate sEV protein and immune function in cancer will provide a potential new direction for cancer treatment." (PMID 36674743, 2023). "Alterations in sEV-related content in cancer cells by inhibiting or activating UBL3 function inhibits cancer cell invasion and metastasis." (PMID 36674743, 2023). "An increasing number of studies has implied that UBL3 expression affects cancer cell growth and cancer prognosis." (PMID 36674743, 2023). "UBL3, as a key molecule affecting DC function, must have the same potential in immunotherapy of cancer." (PMID 36674743, 2023). "Among the universal DEGs, 4 upregulated genes (BGN, E2F3, PLAU, and SPP1) and 1 downregulated gene (UBL3) were found to be cancer genes already documented in the COSMIC or F-Census databases." (PMID 33542925, 2021). "However, further studies on the function of UBL3, its mechanism of action, and its effects on various cancers are still needed to understand UBL3 more deeply." (PMID 36674743, 2023). "The interaction of UBL3 with MMP14 may be to segregate MMP14 into sEVs to inhibit cancer progression." (PMID 36674743, 2023). "Whether UBL3 is an inhibitor or a promoter of cancer, UBL3 has the potential to be a target for cancer therapy." (PMID 36674743, 2023). "The relationship between UBL3 and various cancers has also been gradually uncovered." (PMID 36674743, 2023). "A variety of sEV proteins that affects cancer properties has been found to interact with UBL3." (PMID 36674743, 2023). "UBL3 has the potential to be a key target for cancer therapy." (PMID 36674743, 2023). "These imply that UBL3 may play an important role in cancer invasion and metastasis via sEVs." (PMID 36674743, 2023).
neurodegenerative disease (2 papers, 2024). A disorder of the central nervous system characterized by gradual and progressive loss of neural tissue and neurologic function. "Previous studies have identified 1241 proteins that can interact with UBL3, including more than 22 disease-associated proteins, including molecules associated with neurodegenerative diseases." (PMID 39000460, 2024). "sEVs research in the field of neuroscience is expected to be accelerated by crossbreeding mouse models of sEV-associated neurodegenerative diseases with the newly established mice overexpressing UBL3 in the forebrain." (PMID 39148092, 2024). "In this way, we will be able to fully interpret the effect of MGST3 on the interaction between α-syn and UBL3, providing reliability and therapeutic prospects for the treatment of neurodegenerative diseases." (PMID 39000460, 2024). "This evidence provides a new therapeutic target for MGST3 as a molecule that regulates the interaction of α-syn with UBL3 in neurodegenerative diseases." (PMID 39000460, 2024). "If the relationship between RNA metabolism and protein transport to sEVs in neurodegenerative diseases is elucidated, compounds that affect UBL3 modification may become novel drug candidates, employing innovative therapeutic strategies for neurodegenerative diseases involving RNA metabolism." (PMID 39148092, 2024).
UBL3 also shares sentences with these, for which no sentence is quoted: infection (4 papers); non-small cell lung carcinoma (2); pancreatic cancer (2); prostate carcinoma (2); hepatocellular carcinoma (1); lung adenocarcinoma (1); pituitary adenoma (1); virus infection (1).